MTOR (mechanistic target of rapamycin kinase)
Diseases named in the same sentence as MTOR in open-access papers (continued):
Sharing a sentence is not in itself a finding about the gene and the disease.
lung cancer (continued). "Dactolisib effectively inhibited the PI3K/mTOR pathway in breast and lung cancer cell lines in vitro, through the downregulation of pAkt and pS6, respectively." (PMID 37215954, 2023). "In this study, we observed that the expression of USP5 promoted the progression of lung cancer cells by the mTOR signaling pathway and interacted with PARP1." (PMID 37060095, 2023). "miRNA-499a-5p, highly enriched in EVs from metastatic lung cancer cells, modulates the mTOR pathway in recipient lung cancer cells with concomitant induction of proliferation, EMT, and migration." (PMID 37207158, 2023). "The elevation of CD109 promotes metastasis and drug resistance in lung cancer by activating the epidermal growth factor receptor (EGFR)–protein kinase B (AKT)–mammalian target of rapamycin (mTOR) signaling pathway." (PMID 37373457, 2023). "In many human cancer types, for instance, lung cancer, the overexpression of Akt/mTOR has been reported." (PMID 36721812, 2023). "This review summarizes two main groups of natural compounds, covering diverse structural alkaloids and flavonoids with anticancer properties and their possible mechanisms are reviewed relying on the down-regulation of the Akt/mTOR pathway in lung cancer cells." (PMID 36721812, 2023). "Herein, we have summarized the alkaloids and flavonoids for lung cancer treatment together with all the possible mechanisms of action relying on the Akt/mTOR pathway down-regulation." (PMID 36721812, 2023). "Overall, the PI3K/Akt/mTOR regulators are of more interest to researchers to unravel the real power of the Akt/mTOR targeting strategy in lung cancer therapy." (PMID 36721812, 2023). "MK-2206, an allosteric AKT Inhibitor, showed synergistic responses in combination with carboplatin in lung and ovarian cancer cells while targeting Akt/mTOR axis via ABTL0812 significantly potentiated cisplatin anti-tumor activity in nude mice of lung cancer." (PMID 36773034, 2023). "The major signaling pathways implicated in the pathogenesis of lung cancer include RAF/MEK/ERK, PI3K/Akt/mTOR, and JAK/STAT signaling." (PMID 37568796, 2023). "In a previous study, resveratrol induced cell death via increased autophagy flux in A549 lung cancer cells, and plasma-activated medium induced autophagic cell death via alteration of the mTOR pathway." (PMID 37507864, 2023). "The activation function of Sirt3 on PI3K-AKT and mTOR pathways has been reported in lung cancer cells, which is similar in HT22 cells showed in our results." (PMID 37891608, 2023). "Isoleucyl-tRNA synthetase 2 (IleRS2) affects the proliferation of lung cancer cells by regulating the mTOR pathway." (PMID 38069034, 2023). "Elevated PI3K levels activate downstream AKT and mTOR signaling pathways, leading to rapid proliferation and metastasis of lung cancer cells." (PMID 37182154, 2023). "Combined rapamycin and DNA-PK inhibitor treatment was required to suppress AKT phosphorylation and also decreased 4EBP1 phosphorylation in human lung cancer models, supporting that DNA-PK is involved in regulating mTOR signaling." (PMID 36682716, 2023). "The optimal cutoff value for serum IBIL was 2.5 μg/L with a sensitivity of 27.6% and specificity of 94.25% suggesting that IBLB inhibits the mTOR pathway by altering the activity of the AMPK pathway leading to lung cancer metastasis." (PMID 37064148, 2023). "Reduced levels of FUT7 CpG DNA methylation have been found in lung cancer, especially in LUSC, and FUT7 promotes lung cancer proliferation by activation of the EGFR/AKT/mTOR signal pathway." (PMID 37256139, 2023). "SiRNA knockdown of PIK3CD-L or PIK3CD-S differentially inhibits AKT/mTOR signaling in PCa, breast, colon and lung cancer cell lines." (PMID 37670888, 2023). "The PI3K/Akt/mTOR pathway is chiefly responsible for the development and exacerbation of lung cancers." (PMID 37568796, 2023).
lung cancer (continued). "To explore the role of PARP1/AMPK/mTOR pathway in cell proliferation and metastases in lung cancer, we treated PC‐9 cells with rapamycin and lentivirus transfection." (PMID 36919822, 2023). "In this review, therefore, we pointed out the inhibitors of the Akt/mTOR signaling pathway (by focusing on alkaloids and flavonoids) in different lung cancer cell lines in detail." (PMID 36721812, 2023). "The activation of the protein kinase B (PKB/AKT)–mammalian target of rapamycin (mTOR) pathway is responsible for PD-L1 protein synthesis, leading to immune escape in lung cancer and glioma." (PMID 37175900, 2023). "Nevertheless, FRMD6 expression also contributes to cancer progression by activating the mTOR signaling pathway, similar to what occurs in lung cancer." (PMID 38093305, 2023). "The PI3K/AKT/mTOR pathway plays an important role in lung cancer cell migration and invasion, specifically in the regulation of MMP2 and MMP9." (PMID 37111758, 2023). "SIRT3 promotes autophagy to suppress doxorubicin-induced senescence by inactivating the PI3K/Akt/mTOR pathway in lung cancer cells." (PMID 36834846, 2023). "ERS triggers cell apoptosis in bladder cancer, ovarian cancer, and lung cancer by repressing the PI3K/AKT/mTOR pathway." (PMID 36815904, 2023). "The miR-29 family advances lung cancer progression through the AMPK/mTOR signaling pathway by negatively regulating MTFR1, while miR-15a-5p inhibits metastasis and lipid metabolism in NSCLC." (PMID 38001571, 2023). "Previous studies have shown that ferulic acid inhibits mTOR, resulting in the inhibition of proliferation and metastasis in human lung cancer cells." (PMID 37465088, 2023). "Derivatives of indolo [2,3-a]pyrrolo [3,4-c]carbazole induce senescence by modulating AKT/mTOR/S6K signaling in breast cancer cells, lung cancer cells, and colon cancer cells." (PMID 36834846, 2023). "Recent reports indicated that curcumin suppressed the migration of lung cancer cells by disturbing the signal transduction pathways PI3K/AKT/mTOR." (PMID 37333486, 2023). "The findings suggest that dietary FD promotes lactate metabolic disorders that sensitize lung cancer metastasis through mTOR-signaling-mediated targets." (PMID 36986244, 2023). "In human lung cancer cell line PC9 with Glu746-Ala750 deletion mutation in exon 19 of EGFR, gefitinib inhibited phosphorylated Akt (p-Akt) and phosphorylated mTOR (p-mTOR) expression." (PMID 38201251, 2023). "Considering that PI3K/AKT/mTOR signalling pathway has been extensively reported as a pivotal network in regulating the lung cancer development." (PMID 37742030, 2023). "Pathways in Cancer, a repository of pivotal signaling pathways in malignancies, has spotlighted the integral roles of pathways like ERBB, MAPK, and mTOR in lung cancer pathogenesis." (PMID 37833424, 2023). "T4 induces autophagy in lung cancer cells by inhibiting the PI3K/AKT/mTOR pathway and improves cisplatin sensitivity in A549/DDP cells." (PMID 35794136, 2022). "It was also reported to induce autophagy in nonsmall-cell lung cancer via blocking the PI3K/Akt/mTOR signaling pathway." (PMID 35892383, 2022). "Our analysis of lung cancer context-specific interaction networks of hub genes revealed that deregulated expressions of EGFR/MAP2K1/mTOR/TEAD1/YAP1 in lung cancer mediated abnormal expressions of 151 genes in total in 154 cancer-mediated interactions." (PMID 35655775, 2022). "METTL3 overexpression can activate the PI3K/AKT/mTOR signalling pathway and mTOR-mediated protein synthesis in cancer cells to promote lung cancer progression." (PMID 36276113, 2022). "Of note, the use of CDK4/6 inhibitors in combination with mitogen-activated extracellular signal-regulated kinase (MEK), or mammalian target of rapamycin (mTOR) inhibitors for treating lung cancer are being tested in clinical trials (NCT03170206, NCT02857270)." (PMID 35814226, 2022).
lung cancer (continued). "First, immunohistochemistry (IHC) assays were conducted on tissue microarrays (TMAs) to examine the expression levels of mTOR in PCa specimens derived from EA and AA patients, and specimens derived from prostate, breast, colon, and lung cancer patients." (PMID 36077039, 2022). "Targeting of mTOR is an attractive and promising approach in the development of therapeutic agents against lung cancer." (PMID 36311939, 2022). "Dysregulation of mTOR signaling has been frequently observed in wide variety of cancers, including lung cancer." (PMID 35437691, 2022). "Metformin treatment (10 mM), particularly in combination with rapamycin (an inhibitor of mTOR), reduced the viability of human lung cancer cells that were resistant to cisplatin." (PMID 36672573, 2022). "Six hub genes were screened in relation to lung cancer, including mTOR, NF1, CHD7, ETS1, IL-6, and COL1A1." (PMID 36211008, 2022). "The dysregulated PI3-K/Akt/mTOR activity is known to contribute to the development and maintenance of lung cancer." (PMID 36311939, 2022). "Taking together, finding targeted therapies for AKT/mTOR downstream effectors is essential for the treatment of lung cancer." (PMID 34854221, 2022). "Based on the findings, it was concluded that TBs-C enhances autophagy and induces G1 phase arrest in human lung cancer cells predominantly by inhibiting the PI3K/AKT/mTOR pathway." (PMID 35529455, 2022). "More importantly, BIRC5 promotes lung cancer progression partially by modulating PD-L1 expression via mTOR signaling and inducing tumor immune evasion." (PMID 36046648, 2022). "Similar functional effects of miR-99b-5p on AR/mTOR inhibition, mTOR localization, and apoptosis induction were also shown in colon, breast, and lung cancer cell models." (PMID 36077039, 2022). "PI3K/Akt/mTOR pathway was found to regulate the proliferation, apoptosis, metastasis of lung cancer, and various drugs that inhibit the PI3K axis are currently being tested in a series of clinical trials." (PMID 36612054, 2022). "Although STK11/LKB1 mutant lung cancers carry an unfavorable prognosis, the administration of different chemotherapeutic agents that target mTOR, glutaminase, and PD-L1 has shown to increase survival in NSCLC patients." (PMID 35165542, 2022). "Combined inhibition of mTOR by rapamycin and of MEK by trametinib achieved tumor suppression in lung cancer models carrying KRAS mutations." (PMID 36048281, 2022). "The AKT/mTOR signaling pathway inhibition has been reported to induce autophagy in human fetal neural stem cells fNSCs and human lung cancer cells H460 cells as well as the mouse mammary epithelial cells HC11." (PMID 36172182, 2022). "In lung cancer, TWIST2 induces oxidative stress in cancer cells by regulating the FGF21-mediated AMPK/mTOR signaling pathway and prevents lung cancer from progressing." (PMID 36428665, 2022). "In lung cancer, the regulatory role of miRNAs in mTOR signaling pathway is also a very significant research direction." (PMID 35844793, 2022). "Recent clinical trials studying the effects of glutaminase inhibitors, mTOR inhibitors, and anti-PD-L1 therapy in lung cancer patients have yielded promising results." (PMID 35165542, 2022). "The IHC assay on a TMA containing multiple cancer specimens has shown that the mTOR protein is overexpressed in colon, breast, and lung cancer patient specimens." (PMID 36077039, 2022). "In recent years, emerging genes have been revealed to be the potential therapeutic targets of lung cancer by inhibiting the PI3K/AKT/mTOR pathway, such as SREBP, DOK7V1, HRH3, SLFN5, and FABP5." (PMID 36349192, 2022). "Further verification found that six hub genes were screened in relation to lung cancer, including mTOR, NF1, CHD7, ETS1, IL-6, and COL1A1." (PMID 36211008, 2022).
lung cancer (continued). "Specifically, cotreatment of ononin with PTX induced apoptosis, inhibiting cell proliferation, invasion, migration, and metastasis via blocking the PI3K/Akt/mTOR pathway which was further validated using biomarkers in human lung cancer A549 xenograft mice." (PMID 36605098, 2022). "For example, in a mouse model of lung cancer, upregulation of autophagy via caspase-3 and mTOR inhibition promotes the efficacy of radiotherapy." (PMID 36105077, 2022). "Our IHC, Western blot, and RT-qPCR results have confirmed an overall upregulation of mTOR and downregulation of miR-99b-5p in independent cohorts of patient samples and a panel of cell lines derived from prostate, colon, breast and lung cancers." (PMID 36077039, 2022). "Timosaponin TAIII, a rhizome of Anemarrhena asphodeloides-derived compound, induces apoptosis in lung cancer cells by down-regulating PI3K/AKT/mTOR and Ras/Raf/MEK/ERK pathways." (PMID 36139919, 2022). "We showed that Mito-LND treatment can inhibit mitochondrial bioenergetics, OXPHOS, and glycolysis, and can inactivate AKT/mTOR/p70S6K signaling in lung cancer cells." (PMID 35626143, 2022). "To investigate the reduction of miR-7-5p, we analyzed the lung cancer mRNA data of TCGA, and divided the data into mTORlow group and mTORhigh group according to the mean value of mTOR level in the samples." (PMID 35136028, 2022). "The patient affected by SCCOPT had a residual tumor following chemotherapy which displayed pronounced similarity with neuroendocrine tumors and lung cancer in terms of its microRNA expression profile and mTOR-downstream activation." (PMID 36287116, 2022). "We will also continue to monitor the impact of the miR-199a/Rheb/mTOR axis on the development of resistance to the treatment of tumors in lung cancer, especially about EGFR-TKIs resistance." (PMID 35844793, 2022). "Together, these results unravel a signaling cascade from the IRE1α-mediated UPR to p38 MAPK and to mTOR signaling in KRAS-mutant lung cancer upon NOP56 suppression." (PMID 35039048, 2022). "High SALL4 expression resulted in proliferative, invasive, and anti-apoptotic effects in lung cancer through activation of PI3K/AKT/mTOR signaling." (PMID 35216168, 2022). "Mammalian target of rapamycin (mTOR) acts as a target gene of miR-100-5p in lung cancer controlling cell growth, proliferation and survival." (PMID 35444536, 2022). "NAP, a Nereis virens-derived serine protease, shows antiproliferation and apoptosis in lung cancer cells by down-regulating the PI3K/AKT/mTOR pathway." (PMID 36139919, 2022). "In the present study, we have uncovered a new and unanticipated mechanism by which NOP56 and mTOR signaling cooperate in metabolic stress response in KRAS-mutant lung cancer." (PMID 35039048, 2022). "Another compound 39 can induce apoptosis of lung cancer cells by activating PI3K-Akt-mTOR and endoplasmic reticulum stress pathway, and inhibit migration of lung cancer cells by blocking mitotic process." (PMID 36210835, 2022). "Krukovine, an Abuta grandifolia-derived alkaloid, shows antiproliferation of lung cancer cells by inactivating PI3K/AKT/mTOR/p70s6k and down-regulating ERK." (PMID 36139919, 2022). "In ABCB1-overexpressed and etoposide-resistant A549 lung cancer cells, interferon A can induce the formation of cell autophagy through the mTOR/Beclin1/ATG5 pathway." (PMID 35136409, 2022). "This study provides useful information of resveratrol derivatives RD2 for treating lung cancer via Akt/mTOR inhibition." (PMID 36500361, 2022). "Third, immunofluorescence assays were followed to investigate the expression levels and subcellular distributions of mTOR and its active form phosphorylated mTOR (pmTOR) in prostate, colon, breast, and lung cancer cell lines." (PMID 36077039, 2022).
lung cancer (continued). "Inhibition of key survival proteins such as Akt and mTOR is a promising strategy for cancer treatment since this pathway is the most frequently found dysregulated in cancers including lung cancer." (PMID 36180880, 2022). "Matrine can induce apoptosis in lung cancer cells by regulating the PI3K/AKT/mTOR signaling pathway, and simultaneously downregulating the expression of apoptosis inhibitory protein." (PMID 35684449, 2022). "A549 lung cancer cells were treated with IC50 concentrations of EMD or 24CD for 24 h to examine their effect against mTOR protein." (PMID 36234769, 2022). "After treatment with TBs-C, phosphorylated AKT and mTOR were downregulated, leading to increased p21 expression and G1 phase arrest in the lung cancer cells." (PMID 35529455, 2022). "In this study, we further validated the expression profiles of mTOR and miR-99b-5p in the PCa, colon, breast, and lung cancer specimens and cell lines." (PMID 36077039, 2022). "A number of molecules are involved in the modulation of mTOR signaling, and specific inhibitors show a good performance in prevention and treatment of various tumors including oral cancer, ovarian cancer, and lung carcinoma." (PMID 36304989, 2022). "For instance, interleukin-22 (IL-22) was profoundly elevated in cell cultures of primary CAFs, and CAFs-secreted IL-22 aggravates the proliferation and metastasis of lung cancer cells via the PI3K-Akt-mTOR signaling pathway." (PMID 33819917, 2021). "Everolimus, targeting mammalian target of rapamycin (mTOR), for breast, pancreatic, gastrointestinal, and lung cancers, Renal cell and subependymal giant cell carcinomas." (PMID 34956857, 2021). "Akt/mTOR and RhoA signaling pathway are both critical in lung cancer development, which are reported to be regulated by TNS1." (PMID 33269380, 2021). "Several reports have documented a relationship between the phosphatidylinositol-3-kinase (PI3K)/ protein kinase B (AKT)/ mammalian target of rapamycin (mTOR) pathway and lung cancer." (PMID 34279440, 2021). "Targeting of mTOR is thus an attractive strategy in the development of therapeutic agents against lung cancer." (PMID 34249899, 2021). "A previous study reported that rhein induces apoptosis through the PI3K/AKT/mTOR signaling pathway in A549 human lung cancer cells and inhibits autophagy by regulating AMPK/mTOR signaling in rat renal tubular cells." (PMID 33946531, 2021). "This study applied a mouse model of lung cancer based on CRISPR/Cas9 technology to functionally address key regulators of the mTor pathway, STK11 and PTEN." (PMID 33652656, 2021). "Artocarpin was able to decrease the active form of mTOR (phosphorylated at Ser2448) in tested lung cancer cells at the concentrations of 5-10 μM (p < 0.05)." (PMID 33920031, 2021). "The release of regulation of PI3K/Akt/mTOR signal transduction pathway can promote the development of lung cancer, while the application of PI3K inhibitors such as LY294002 can promote NSCLC apoptosis." (PMID 34017995, 2021). "In lung cancer, a high Pi intake (a diet fortified with 1.0% Pi) led to pulmonary tumour progression via the Akt-mTOR regulatory pathway." (PMID 34576256, 2021). "Our results elucidated a novel mechanism whereby ZVI-NP disrupts redox balance and induces ferroptosis of lung cancer cells by triggering AMPK/mTOR signaling to promote GSK3β/β-TrCP degradation of NRF2." (PMID 34093872, 2021). "For example, PI3K/mTOR signaling is activated in lung cancer, and drugs targeting this signaling pathway are being investigated." (PMID 34082790, 2021). "For the first time, we found that the PI3K/Akt/mTOR/STAT3 pathway was also involved in the effect of leptin on lung cancer cell growth." (PMID 33708630, 2021). "A recent study revealed that ginkgolic acid can affect the EMT of lung cancer cells by downregulating the AKT/mTOR pathway, thereby inhibiting migration and metastasis." (PMID 34255431, 2021).